TSC2 (TSC complex subunit 2)
Diseases named in the same sentence as TSC2 in open-access papers (continued):
Sharing a sentence is not in itself a finding about the gene and the disease.
tumor (continued). "It is caused by mutations in either of the two genes, TSC1 or TSC2, which code for the proteins hamartin (chromosome 9q34) and tuberin (chromosome 16p13), respectively, that act as tumour-growth suppressors." (PMID 24884933, 2014). "In fact, clinical tumor samples demonstrating a loss of functional TSC1/TSC2 also showed loss of mTORC2 function." (PMID 25283550, 2014). "TSC1 and TSC2 mutations cause neoplasms in rare disease pulmonary LAM and neuronal pathfinding in hamartoma syndrome TSC." (PMID 25360538, 2014). "A hotspot for mutations in tsc2 involves regions implicated in controlling rheb, although multiple other signaling pathways have also been linked to TS-related neoplasia, including mTORC1, notch, p42/44 MAP kinase, NFkB, and Akt." (PMID 22765013, 2012). "Since rapamcyin has previously been shown to cause a marked reduction in tumor volume in Tsc2+/− mice, it was given for one month only, as we have done previously." (PMID 22363765, 2012). "To measure the effect of estrogen, we implanted male and female mice with estradiol pellets or placebo pellets 7 to 10 days before inoculation of tumor TSC2-deficient cells." (PMID 22719903, 2012). "In particular, we found a novel androgen-dependent mRNA isoform derived from an alternative internal promoter within the TSC2 tumour suppressor gene, which is predicted to encode a protein lacking an interaction domain required for mTOR inhibition." (PMID 22194994, 2011). "We also used a Tsc2-/- subcutaneous tumor model that reflects the loss of heterozygosity (LOH) observed in TSC-related kidney and brain tumors as a generic model for TSC-related tumors." (PMID 19368729, 2009). "TSC is caused by mutations in the TSC1 or TSC2 genes, whose products, hamartin and tuberin, form a tumor suppressor complex that regulates the PI3K/Akt/mTOR pathway." (PMID 19368729, 2009). "In these models, homozygous TSC1 or TSC2 mutants die at an embryonic stage, whereas heterozygous carriers are predisposed to tumour formation." (PMID 19506736, 2008). "Loss of heterozygosity studies at the TSC1 and TSC2 loci in TSC-associated lesions indicate that TSC1 and TSC2 are tumour suppressor genes." (PMID 18302728, 2008). "Mutations of the TSC1 and TSC2 genes can affect the mechanistic target of the rapamycin (mTOR) signaling pathway and thus disrupt the regulating mechanisms of cell growth and proliferation, leading to tumor development." (PMID 40723161, 2025). "Notably, TSC1 and TSC2 emerge as the most frequently mutated genes linked to activated mTOR signaling in HCC tumor samples." (PMID 39863613, 2025). "Mutations in TSC1/TSC2 can lead to mTOR overactivation, promoting tumor growth." (PMID 38731914, 2024). "To test this hypothesis, we asked whether loss of Tsc2 is sufficient to rescue loss of the tumor-inhibiting effects of Rictor." (PMID 39325536, 2024). "Therefore, abnormal mTOR activation via loss of functional Tsc1 or Tsc2 promotes oncogenesis by maintaining the necessary cellular signals for tumor growth, survival, and proliferation." (PMID 39352796, 2024). "TSC1 and TSC2 are classified as tumor suppressor genes and function according to Knudson’s two-hit hypothesis, which requires both alleles to be damaged for tumor formation." (PMID 37232723, 2023). "Molecular analysis of the tumor confirmed loss of heterozygosity and allelic mutation of TSC2 gene." (PMID 36769603, 2023). "The TSC1 (9q34) and TSC2 (16p13.3) genes encode two tumor suppressor subunits, TSC1–Subunit 1 or Hamartin (1164 amino acids; 129,767 Da) and TSC2–Subunit 2 or Tuberin (1807 amino acids; 200,608 Da) of the TSC complex, which negatively regulates anabolic cell growth." (PMID 37509254, 2023). "This suggested that loss-of-function TSC2 may alter the TNBC tumor microenvironment and that immunotherapy may be effective for patients with TNBC." (PMID 37251941, 2023). "Notably, Tsc1 interaction with Tsc2 was compromised in this model resulting in loss of Tsc2 tumor suppressive function." (PMID 35883484, 2022).
tumor (continued). "TSC is characterized by broad phenotypic heterogeneity, suggesting that other events beyond TSC1/TSC2 biallelic loss may act as disease modifiers and susceptibility loci for tumor development." (PMID 36793390, 2022). "Overall, these results indicate that eFT226 hinders Tsc2-deficient tumor growth." (PMID 35805935, 2022). "The proportion of PD-L1high/CD8Ahigh was 41.4% in the TSC2low group, significantly higher than the 28.2% in the TSC2high group (P < 0.01), indicating that TSC2-loss tumor displayed an inflamed TME, which had been demonstrated to be associated with benefits from immunotherapy." (PMID 35119931, 2022). "Collectively, our data derived from cell lines, syngeneic mouse models, and specimen of patients with NSCLC revealed the prominent significance of TSC1/TSC2 mutations in promoting PD-L1 expression, facilitating T cell infiltration and augmenting tumor immunogenicity." (PMID 35119931, 2022). "LAMA1 and AHNAK has been implicated in tumor metastasis while TSC2 is considered tumor suppressor." (PMID 36026497, 2022). "Tumor-driver mutations in genes other than TSC2 may have a role in S-LAM, and TBLB specimens are practical alternatives for genomic analysis." (PMID 36117164, 2022). "In our studies, targeting the SPHK1/S1PR3 axis with inhibitors reduced the expression of SPHK1 and S1PR3 and the biosynthesis of S1P (data now shown), significantly suppressed TSC2-deficient cells metastasis and prolonged the survival of mice carrying xenograft tumor." (PMID 36543771, 2022). "Our data fit the model that additional TSC2 mutations occur in small clonal populations of dermal fibroblasts that are undergoing clonal expansion but are not recognized clinically; these clonal populations represent a tumor that we call a micro-FAF." (PMID 35358092, 2022). "While mTORC1 hyperactivation upon the loss of TSC1/TSC2 is a well-defined aspect of TSC that is mechanistically linked to tumor growth, we hypothesize that mTORC1-independent signaling mechanisms are also critically involved in the development of TSC." (PMID 36551683, 2022). "Notably, 8 autophagy-related genes (CAPN10, DAPK2, MBTPS2, ST13, CFLAR, FADD, PEX14 and TSC2) and 2 immune cells (Mast cells and Eosinophils) were revealed to be highly associated with tumor prognosis." (PMID 34093817, 2021). "TSC1 (9q34) and TSC2 (16p13), both known tumor suppressors, are the causative genes." (PMID 34465349, 2021). "We assessed whether this deleterious variant in TSC2 was expressed in mRNA using RNA-Seq data from the tumor sample." (PMID 34465349, 2021). "Furthermore, infusion of mice with TSC2-deficient or TSC2-overexpressing monocytes promote or reduces tumor angiogenesis and growth in murine xenografts by modulating macrophage polarization, respectively." (PMID 35250965, 2021). "Through genetic and pharmacological inhibition of autophagy, it was possible to verify that TSC2-deficient tumor cells derived from LAM could be dependent on autophagy to survive." (PMID 33821877, 2021). "The mutation in the TSC2 tumor suppressor causes aberrant cell growth and therefore may contribute the tumor progression and metastasis of CRC." (PMID 35860598, 2021). "In monotherapy, these drugs provided significant inhibition of Tsc2‐deficient 105 K tumor growth." (PMID 34378323, 2021). "Additionally, tumor development in TSC fits the Knudson two-hit tumor-suppressor gene model with a second hit event causing the inactivation of the remaining wild-type allele of either TSC1 or TSC2." (PMID 32075691, 2020).
tumor (continued). "Any mutation or amplification of the upstream effectors of mTORC1 or loss of function of the tumor suppressors that inhibit mTORC1, like TSC2, could lead to overstimulation of mTORC1 and drive tumor progression." (PMID 33020720, 2020). "Experimental animal studies have previously shown that early-life exposure to DES leads to loss of function of the normal Tsc2 allele, particularly in the reproductive system, which may develop neoplastic diseases such as UFs." (PMID 32545544, 2020). "Tumor suppressor TSC2 is a negative regulator upstream of mTOR and its inactivating mutations cause tuberous sclerosis complex, an autosomal dominant syndrome which results in tumor development in multiple organs." (PMID 32308763, 2020). "Furthermore, Syk inhibitor fostamatinib reduced the proliferation of TSC2-deficient cells in vitro and suppressed TSC2-null xenograft tumor development in vivo." (PMID 33072782, 2020). "Our findings therefore point to very low-grade mosaicism for the TSC2 variant, possibly in a yet unknown mesenchymal precursor cell that expanded clonally during tumor development." (PMID 31077186, 2019). "Treatment with eFT508 in vivo might be additive with rapamycin or checkpoint inhibitors via the enhancement of the immune defense against TSC2-deficient tumor growth." (PMID 31878201, 2019). "Sanger sequencing validated this finding, and detected the TSC2 mutation also in the primary tumor." (PMID 29764404, 2018). "Also, the difference in tumor initiation between TSC2-deficient MEFs with intact (control) or impaired eIF2αP decreased from 23 days under RD to 10 days under AOD (compare graphs e and g with graphs f and h, respectively)." (PMID 29449538, 2018). "Also, decreased eIF2αP delays the initiation of tumor formation of TSC2-deficient cells in immune deficient mice, an effect that is significantly alleviated in mice kept on an anti-oxidant diet." (PMID 29449538, 2018). "We next examined whether inhibition of tumor initiation of TSC2-deficient cells by eIF2αP is affected by pro-oxidant conditions in the tumor microenvironment." (PMID 29449538, 2018). "In addition to accelerated tumor initiation, TSC2-proficient tumors exhibited better growth rates than the TSC2-deficient tumors (compare graphs a and g)." (PMID 29449538, 2018). "Importantly, miR-21 inhibition limited Tsc2-deficient tumor growth in vivo, reducing tumor size by approximately 3-fold (p<0.0001)." (PMID 29029388, 2017). "Finally, in an in vivo xenograft mouse model, miR-21 inhibition limited Tsc2-deficient tumor growth with substantial reductions in tumor-free survival and tumor volume." (PMID 29029388, 2017). "Finally, we found 3 pathogenic/likely-pathogenic mutations in ERCC3, RECQL4 and TSC2 genes, encoding transcription factors and tumor suppressors." (PMID 28423363, 2017). "Tsc2−/− MEFs transfected with lentiviral vector encoding PDGFRα or empty vector were subcutaneously injected into the right anterior armpit of nude mice, and then tumor growth was monitored." (PMID 28903387, 2017). "To determine whether the drug combination was successful in a 3D setting, we next tested nelfinavir and salinomycin within Tsc2-deficient tumour spheroid model systems." (PMID 28415776, 2017). "Furthermore, this drug combination also inhibited tumour formation in TSC2-deficient cell models and caused tumour spheroid death in 3D culture." (PMID 28415776, 2017). "TSC1 or TSC2 loss of function and subsequent mTORC1 activation, which drives tumor formation and vascular changes, have been investigated using rodent models, exploiting a spontaneous mutation in Tsc2 in the Eker rat, or using targeted disruption of Tsc1 or Tsc2 in mice." (PMID 28695825, 2017). "These tumours also almost invariably display biallelic loss of TSC2 or more rarely of TSC115–17,19." (PMID 29133867, 2017).
tumor (continued). "Tuberous sclerosis complex (TSC) is an autosomal dominant disorder characterized by the formation of benign tumors in multiple organs including kidney, brain, skin, and heart, which is caused by inactivating mutations in either of two tumor suppressor genes: TSC1 or TSC2." (PMID 28903387, 2017). "Urotensin receptor antagonists may be selective therapeutic agents for the treatment of LAM or other neural crest-derived neoplasms featuring loss of TSC2 or increased expression of the urotensin receptor." (PMID 27458154, 2016). "Notably, all seven tumours with TSC1 or TSC2 mutations had high level of p-4EBP1 (H score=300), whereas only two of four tumours with PTEN mutations exhibited such staining." (PMID 27713405, 2016). "Sequencing of the pretreatment tumor demonstrated a nonsense TSC2 mutation." (PMID 26255626, 2015). "Sequencing this patient's tumour DNA revealed a TSC2 mutation." (PMID 26410619, 2015). "Restoration of TSC2 suppresses cell proliferation in Tsc2-deficient tumor cells." (PMID 23355874, 2013). "Interestingly, similar tumor cell deposition patterns were seen, demonstrating that the TSC2-deficient cells in vivo retained tumorigenicity and were disseminated systemically, although the tumor take rate and latency varied in different administrations." (PMID 22719903, 2012). "Further analysis of the Pten, TSC1, and TSC2 tumor suppressor genes demonstrated their loss-of-function condition resulted in severely altered blood cell homeostasis, including the abundant production of lamellocytes, specialized hemocytes involved in innate immune responses." (PMID 22911822, 2012). "In addition, neutrophil elastase (NE) is predominantly expressed and secreted by neutrophils, and RNA and protein analyses of TSC2-deficient uterine myometrial tumors and xenografts indicate high expression and activity of NE promoting in vitro growth, migration, and invasion of tumor cells." (PMID 40600043, 2025). "Notably, mTOR activity is activated by mutations in a variety of oncogenes and tumor suppressors, suggesting the possibility that TSC2 might be a commonly mutated tumor suppressor." (PMID 38117060, 2024). "In addition, one case achieved a near CR within 18 months and found that the anti-oncogene TSC2 in this patient’s pretreated tumor tissue contained a somatic nonsense mutation that reactivated the mTOR pathway, which may reveal a mechanism of drug resistance." (PMID 36612173, 2022). "Therefore, the microenvironment of TSC2-deficient tumor cell might promote high expression of CD24 in macrophages to induce autoimmune escape." (PMID 36231025, 2022). "Our data indicate that a negative feedback loop constrains amino acid-induced, FLCN:FNIP2-mediated RagC activity in renal cells with constitutive mTORC1 signaling, and the resulting MiT/TFE hyperactivation may drive oncogenesis with loss of the TSC2 tumor suppressor." (PMID 36357396, 2022). "Similarly, TSC2 mutations weaken mTOR regulation, leading to tumor cell proliferation and hypoxia." (PMID 36059442, 2022). "The mutation of TSC2 may induce the formation of tumours by affecting mTOR inhibition." (PMID 34085405, 2021). "Furthermore, tumor suppressor effect of “tuberous sclerosis complex 2” protein (TSC2) activated by ROS induced “ataxia-telangiectasia mutated” (ATM) protein may have also decreased the expression of mTORC1 gene." (PMID 33539381, 2021). "We next sought to determine whether the AML-like tumour and cellular phenotypes observed in our system are specifically related to the Tsc2 and Cdkn2a loss-of-function genotype or whether any genetic combination that causes transformation and sphere formation would give similar results." (PMID 29133867, 2017). "In addition to TSC1/TSC2, we hypothesized that lesions may acquire mutations in other genes, including those that affect tumour growth." (PMID 28643795, 2017). "We investigated alternative mechanisms of neoplasia that might be specific to TSC2-deficient cells." (PMID 27458154, 2016).
tumor (continued). "Furthermore these observations suggest that there is likely a specific cell type (currently unknown) that is resident in the early kidney that is sensitive to the tumor and growth promoting effects of TSC2 or TSC1 loss." (PMID 27494029, 2016). "Mechanistically, UBE2L3 downregulation led to increased tuberous sclerosis complex 2 (TSC2) expression, suppressing mTOR activity and altering autophagic processes in tumor cells." (PMID 41943836, 2026). "In the rare and aggressive Scirrhous-HCC subtype, which is characterized by dense fibrous stroma and small tumor nests, frequent Tuberous Sclerosis Complex 1 (TSC1)/Tuberous Sclerosis Complex 2 (TSC2) mutations have been prevalent." (PMID 41522204, 2026). "It is well-established that RHEB is a small GTPase that directly activates mTORC1 activity, but is negatively regulated by tumor suppressors TSC1/TSC2." (PMID 39762645, 2025). "In conclusion, our study identifies mutations in LRP1B, KMT2B, TSC2 and BRAF as significant prognostic markers in T1/2 CRC, along with critical clinical features such as lymphovascular invasion, poor tumour differentiation and aggressive histological types." (PMID 39777996, 2025). "PTEN and TSC2 act as tumor suppressors by negatively regulating AKT, a key activator of mTOR signaling." (PMID 41465847, 2025). "TSC is caused by heterozygous pathogenic variants in either the TSC complex subunit 1 (TSC1) or the TSC complex subunit 2 (TSC2) tumor suppressor genes, which lead to overactivation of the rapamycin (mTOR) pathway and tumor formation in multiple organs." (PMID 40861726, 2025). "Experimental studies have identified recurrent mutations in MEN1, ATRX, DAXX, TSC2, and PTEN, with MEN1 and ATRX alterations significantly associated with tumor burden in approximately 40% of cases." (PMID 40869136, 2025). "As tumor suppressor genes, mutation and inactivation of TSC1/TSC2 enable cells to evade immune surveillance, promote tumor‐related protein expression, and contribute to tumorigenesis." (PMID 41383536, 2025). "An inactivating mutation in two tumor-suppressor genes—TSC1 and TSC2—is the cause of this syndrome, and TSC2 mutations make up 80–90% of all mutations." (PMID 39852149, 2025). "Studies on the TSC/mTOR pathway highlight its critical role in tumor biology, positioning TSC2 as a crucial target for developing precision medicine strategies to treat cancers associated with mTOR dysregulation." (PMID 41181577, 2025). "An inactivating mutation in two tumor-suppressor genes—TSC1 and TSC2—is the cause of this syndrome, and TSC2 mutations made up 80–90% of all mutations." (PMID 39852149, 2025). "When TSC2 function is impaired, mTOR/4EBP1/c‐Myc signaling becomes abnormally activated, enhancing tumor stemness." (PMID 40433832, 2025). "PTEN and TSC2 share similar biological functions in inhibiting tumor growth and regulating tissue and organism size." (PMID 39901197, 2025). "Instead of a second somatic mutation of TSC2 during tumour progression, CLIP cells lose their healthy TSC2 allele due to copy-neutral LOH, the exchange of large genomic regions between homologous chromosomes." (PMID 40655946, 2025). "In this study, we used chronic treatment with rapamycin on TSC1/TSC2-mutant tumor cell lines, including human BLCA, HCC, and AML, and mouse RCC, to generate rapamycin-persistent (RP) derivatives." (PMID 41277553, 2025). "Currently, one key feature of TSC1/TSC2 biology is well understood: the ability of the TSC1/2 tumour suppressor complex to inhibit growth signalling through mechanistic target of rapamycin complex 1 (mTORC1)." (PMID 39070657, 2024). "The idea of a combination treatment is not new in LAM, as in 2015, Alayev and colleagues reported promising results from combining Rapamycin with resveratrol, an autophagy inhibitor, in a Tsc2-null xenograft tumor model." (PMID 39456169, 2024).